EPO (erythropoietin)
Diseases named in the same sentence as EPO in open-access papers (continued):
Sharing a sentence is not in itself a finding about the gene and the disease.
diabetic nephropathy (26 papers, 2013 to 2026). "A previous study indicated that older age, high body mass index, pretreatment for Hb, use of angiotensin conversion enzyme/angiotensin receptor blocker, and diabetic nephropathy were associated with increased erythropoietin requirements in anemic p-CKDs." (PMID 36966289, 2023). "Diabetic nephropathy is associated with erythrocyte fragmentation, and renal dysfunction is often accompanied by deficiency of erythropoietin, thus leading to increased RDW." (PMID 35658957, 2022). "T allele of genetic variant rs1617640 in EPO gene was a risk allele for diabetic nephropathy in this meta-analysis." (PMID 25280384, 2014). "In addition, diabetic nephropathy caused by ongoing hyperglycaemia results in the destruction of the renal interstitium which is composed of interstitial peritubular fibroblast, further causing the impairment in erythropoietin (EPO) production." (PMID 31828165, 2019). "This increased incidence of IDA in diabetic patients is driven by several interconnected mechanisms, such as diminished erythropoiesis due to decreased erythropoietin production in diabetic nephropathy." (PMID 41155185, 2025). "In contrast, other ESRD patients, such as those with diabetic nephropathy, hypertensive nephropathy, and chronic glomerulonephritis, completely lose their ability to produce EPO." (PMID 41554511, 2025). "Regarding the cause of end-stage kidney disease, AQP3 expression positively correlated with erythropoietin dosages in the chronic glomerulonephritis (GN) subgroup (R = 0.6; P = 0.003), but negatively in the diabetic nephropathy subgroup (R = -0.59; P = 0.004)." (PMID 36038817, 2022). "Renal dysfunction also caused by ROS through hyperglycaemia has been shown to be associated with a decrease in EPO concentration as interstitial fibroblasts responsible for EPO secretion are often destroyed during the development of diabetic nephropathy." (PMID 31828165, 2019). "Potential confounders of this relationship are decreased erythropoietin production due to diabetic nephropathy and nutritional and socioeconomic status." (PMID 28767669, 2017). "Potential confounders of the association between hemoglobin and retinopathy are socioeconomic and nutritional status and decreased erythropoietin production due to diabetic nephropathy." (PMID 27406115, 2016). "Second, reactive oxygen species (ROS) induce endothelial cell dysfunction, subsequently leading to glomerular diseases, including diabetic nephropathy, as well as hypoxic conditions involved in EPO-mediated erythropoiesis." (PMID 26098847, 2015). "In this meta-analysis, variants within or near VEGFA (two variants), CCR5 (two variants), CCL2, IL-1, MMP9, EPO, IL-8, ADIPOQ and IL-10 were significantly associated with diabetic nephropathy." (PMID 25280384, 2014). "In addition, restoring the contents of endothelial nitric oxide synthase, due to the activation of the PI3K/Akt pathway, contributed to the prevention of diabetic nephropathy by EPO." (PMID 40943240, 2025). "In diabetic retinas, EPO protects retinal cells by upregulating ZnT8 via ERK pathway activation and HIF-1α expression inhibition, and EPO may slow progression of diabetic nephropathy (DN)." (PMID 29348855, 2017).
Hyperglycemia (25 papers, 2013 to 2025). An increased concentration of glucose in the blood. "Chronic hyperglycemia can cause a persistent hypoxic environment in the renal interstitium which results in impaired erythropoietin production." (PMID 36730249, 2023). "The authors suggested the existence of a compensatory effect in younger T1D patients that may be linked to erythropoietin stimulation in response to hyperglycemia." (PMID 40710089, 2025). "EPO expression was found to be more abundant in RPE than in the neuroretina, which supported the notions that EPO is actually produced in the local microenvironment of the eye and that ischemia and hypoxia caused by hyperglycaemia may be stimulating factors." (PMID 34621759, 2021). "Persistent hyperglycemia can create a hypoxic environment in the renal interstitium, leading to impaired erythropoietin production." (PMID 40655101, 2025). "Plant-derived OA alleviated hyperglycemia and reduced hemoglobin A1c (HBA1c) and erythropoietin (EPO) concentrations in STZ-induced diabetic rats." (PMID 39064870, 2024). "When fetal blood oxygen levels decrease as a result of hyperglycemia, fetal plasma erythropoietin (EPO) levels increase sharply due to increasing fetal EPO synthesis." (PMID 34151398, 2021). "Untreated diabetic rats exhibited hyperglycaemia, elevated glycated haemoglobin (HbA1c), oxidative stress, and a reduced erythropoietin (EPO) concentration when compared to ND rats." (PMID 31828165, 2019). "Amelioration of hyperglycemia by regular injections of recombinant human EPO (rhEPO) has been described in rodents, but similar to previous studies about hypoxia conclusions were hampered by an unaccounted influence of weight differences and/or hematocrit-sensitive glucose meters." (PMID 40238885, 2025). "Furthermore, persistent hyperglycemia will change blood composition, such as erythrocyte morphology, and increase the production of erythropoietin (EPO)." (PMID 38398510, 2024). "The increased erythropoietin production and decreased life span of red blood cells in pregnancy may make HbA1c an unsuitable marker for screening hyperglycaemia." (PMID 39548720, 2024). "Inhibition of SET7/9 methyltransferase activity by Set7_1a led to reduced HIF-1α methylation at the lysine 32 residue, causing increased HIF-1α level and recruitment of HIF-1α target genes that promote angiogenesis, such as VEGF, GLUT1, and EPO, in hypoxia and hyperglycemia." (PMID 35859119, 2022). "Chronic hyperglycemia could lead to a cellular hypoxic state in the renal interstitium, which contributes to impaired production of erythropoietin in renal peritubular fibroblasts." (PMID 34789178, 2021). "However, administration of OA attenuated hyperglycaemia, HbA1c, and EPO concentrations compared to DC rats." (PMID 31828165, 2019). "Our results showed that OA reduces hyperglycaemia, further improving erythrocyte function possibly through the increase in EPO secretion, improvement of antioxidant status, and decrease of glycated haemoglobin and by improving cell survival for the whole lifespan of the erythrocyte." (PMID 31828165, 2019). "The results of the present study demonstrated a relationship between inflammatory factors and hyperglycemia after IRI and suggested that erythropoietin may be useful for preventing brain IRI, but its higher doses should be used with caution due to possible side effects." (PMID 30719249, 2018).
hypoxic-ischemic encephalopathy (25 papers, 2011 to 2025). "In a paper studying hypoxic-ischemic encephalopathy, EPO’s neuroprotective effects were modulated via the phosphorylation of MAPK." (PMID 36978804, 2023). "In this phase II trial, newborns with moderate/severe encephalopathy and perinatal depression were randomly assigned to receive either EPO (1000 U/kg intravenously; n = 24) or a placebo (n = 26) at specific intervals in the first week of life." (PMID 37892791, 2023). "In human trials, EPO administration in neonates with hypoxic ischemic encephalopathy (HIE) significantly reduced the neurological hypoxemic damages in several reported studies." (PMID 34912224, 2021). "The electronic databases of Cochrane Library, EMBASE, PubMed, and Web of Science were searched from the inception to June 2021 using the following key terms: “erythropoietin,” “hypoxic-ischemic encephalopathy,” and “prospective,” for all relevant RCTs." (PMID 34128891, 2021). "Multiple clinical trials have demonstrated the safety and efficacy of erythropoietin in improving neurodevelopmental outcomes in infants with hypoxic-ischemic encephalopathy (HIE)." (PMID 34128891, 2021). "High-dose human recombinant erythropoietin (rEPO) is a promising potential neuroprotective treatment in preterm and full-term neonates with hypoxic-ischemic encephalopathy (HIE)." (PMID 32344930, 2020). "In infants with extreme prematurity, hypoxic-ischemic encephalopathy, perinatal stroke, and complex cyanotic heart disease, trials have demonstrated safety, and the potential for efficacy of erythropoietin." (PMID 31850291, 2019). "Actually, in the clinical trials, erythropoietin showed neuroprotective effect against acute stroke, hypoxic-ischemic encephalopathy in newborns and delayed ischemic deficits following aneurysmal subarachnoid hemorrhage." (PMID 22216265, 2011). "Our review found that erythropoietin has promising effects as a neuro-regenerative treatment in the preterm population (yellow light, weak positive) and erythropoietin trials are underway in a population with hypoxic ischemic encephalopathy [11••]." (PMID 32086598, 2020). "Multiple doses of EPO may improve neuroimage findings and motor function in neonates with hypoxic-ischemic encephalopathy." (PMID 29385149, 2018). "Exogenous EPO therapy has shown particular promise as a neuroprotective agent in neonates affected by Hypoxic Ischemic Encephalopathy (HIE), a hypoxic brain insult that occurs at or around the time of birth and is associated with significant neurodevelopmental morbidity." (PMID 29084993, 2017). "The EPO group had a significantly higher rate of status post-intraventricular hemorrhage (23.1% vs. 12.3%, p = 0.024) and status post-hypoxic-ischemic encephalopathy (30.6% vs. 11.5%, p = 0.002) compared with the No EPO group." (PMID 38804373, 2024). "In this secondary analysis of a randomized clinical trial of 180 neonates with hypoxic ischemic encephalopathy and complete biomarker and outcome data, erythropoietin treatment did not affect the measured circulating biomarker concentrations." (PMID 37418263, 2023). "The effectiveness of EPO in combination with hypothermia has been demonstrated in a term nonhuman primate model of perinatal asphyxia, based on umbilical cord occlusion for 15 to 18 minutes." (PMID 28134843, 2017). "This study aimed to investigate the impact of early erythropoietin (EPO) administration on the neurodevelopment of newborns, specifically focusing on its effects on hypoxic-ischemic encephalopathy (HIE) and intraventricular hemorrhage (IVH)." (PMID 38804373, 2024). "First, EPO concentration was not measured longitudinally, even though this had been performed in our first rhEPO clinical studies (during which rhEPO was administrated to term infants with hypoxic ischemic encephalopathy)." (PMID 33076939, 2020).
renal dysfunction (25 papers, 2011 to 2025). "The findings from this study that the impaired hematological status is associated with renal dysfunction can be explained by the observed decrease in erythropoietin." (PMID 39435383, 2024). "Renal anemia is generally caused by a decrease in the production of erythropoietin in kidney due to renal dysfunction, and this may be associated with the increase in mortality and cardiovascular events in addition to subjective symptoms such as fatigue and wobbliness." (PMID 38974395, 2024). "The development of RBCs is regulated by erythropoietin, which is mainly produced by the kidneys, and the level of erythropoietin is de-creased in renal dysfunction patients." (PMID 36744052, 2023). "Renal dysfunction also results in decreased erythropoietin, which is reported to have a cardioprotective role." (PMID 35845008, 2020). "In parallel, renal dysfunction can blunt erythropoietin production, while intestinal congestion and edema impair iron absorption; intravascular volume expansion may also lower measured hemoglobin via hemodilution." (PMID 41367439, 2025). "These patients had mild renal dysfunction, bilateral renomegaly, and increased EPO levels." (PMID 39190047, 2025). "Mild renal dysfunction is suspected to enhance renal erythropoietin production in early-stage CKD." (PMID 39064247, 2024). "Although renal dysfunction is frequent in HF, such structural renal diseases that could reduce EPO production are scarce." (PMID 35204607, 2022). "Prognostic value of EPO in our study was independent from mild-to-moderate renal dysfunction." (PMID 33330669, 2020). "Risk factors for late PTA include renal dysfunction, history of rejection, longer duration of transplantation and not using EPO in the pre-transplant period." (PMID 21827693, 2011). "Besides, renal dysfunction increases blunted EPO production in anemic patients with HF." (PMID 35581275, 2022). "Multivariate analysis showed that renal dysfunction and not using EPO before transplantation were major predictors for PTA." (PMID 21827693, 2011). "Renal dysfunction and not using EPO in the pre-transplant period are major predictors of PTA." (PMID 21827693, 2011). "Renal dysfunction and not using EPO in the pre-transplant period are major predictors of late PTA." (PMID 21827693, 2011).
Parkinson disease (23 papers, 2009 to 2026). A progressive degenerative disorder of the central nervous system characterized by loss of dopamine producing neurons in the substantia nigra and the presence of Lewy bodies in the substantia nigra and locus coeruleus. "Parkinson's disease (PD) is caused by oxidative stress, and erythropoietin (EPO) reduces oxidative stress in the brain." (PMID 25136634, 2014). "In conclusion, systemic administration of a high dose of EPO exerted neuroprotective effects in reversing behavioral deficits associated with Parkinson’s disease and prevented loss of the dopaminergic neurons through the MAPK pathway." (PMID 24939444, 2014). "We have recently demonstrated that adeno-associated virus serotype 9 (AAV9)-mediated human erythropoietin (hEPO) gene delivery into the brain protects dopaminergic (DA) neurons in the substantia nigra in a rat model of Parkinson's disease." (PMID 23667683, 2013). "Studies have demonstrated that systemic administration of erythropoietin (EPO) in animal models of induced Parkinson's disease yields a pronounced neuroprotective effect." (PMID 39744428, 2025). "As a neuroprotective factor, EPO is also used in the treatment of various diseases, such as neurodegenerative diseases, Parkinson’s disease, traumatic brain injury, by decreasing inflammatory reaction, resisting apoptosis, and lowering oxidative stress." (PMID 35167649, 2022). "Neural precursors naturally releasing EPO were applied to an MPTP-induced mouse model of Parkinson’s disease." (PMID 27789613, 2016). "EPO also can limit oxidative stress injury during cisplatinum administration and in models of Parkinson’s disease." (PMID 23109841, 2012). "EPO has also been examined for neuroprotective effects in a mouse model of Parkinson’s Disease." (PMID 36816125, 2023). "For these reasons, treatment of Parkinson’s disease with EPO could be a potentially useful to fight oxidative stress." (PMID 33467745, 2021). "We used EEG source analysis to identify which cortical areas were involved in the automatic and controlled processes of inhibitory control on a flanker task and compared the potential efficacy of recombinant-human erythropoietin (rHuEPO) on the performance of Parkinson's Disease patients." (PMID 32566122, 2020). "Moreover, our data suggests that erythropoietin can be a potential pharmacological therapy useful for the treatment of Parkinson’s disease, thanks to its anti-inflammatory properties." (PMID 30501635, 2018). "Moreover, a brain penetrating IgG-erythropoietin fusion protein was constructed which shows neuroprotective effects following an intravenous treatment in Parkinson's disease in the mouse." (PMID 25136634, 2014). "EPO is a well-known hematopoietic hormone with demonstrated neuroprotective effects for diseases in the central nervous system, including cerebral ischemia and Parkinson’s disease." (PMID 24287913, 2013). "The erythropoietin-mediated neuroprotective effects have been reported in diverse studies of ischemia, parkinsonism, brain trauma, seizures and epilepsy, as well as its therapeutic effects, in different neurological disorders, such as stroke, schizophrenia and Parkinson’s disease, among others." (PMID 33202963, 2020). "Recently, the favorable effect of erythropoietin (EPO) on mitochondrial functionality was examined in both in vivo and in vitro models of Parkinson’s disease, in which augmented oxidative stress leads to mitochondrial disfunction, neuronal apoptosis, and cell toxicity." (PMID 36835089, 2023). "EPO demonstrated little evidence of cognitive benefits among patients with schizophrenia, bipolar disorder, or Parkinson’s disease." (PMID 29670547, 2018).
Parkinson disease (continued). "Furthermore, our recent data suggest robust neuroprotective effects, but without hematopoietic consequences, by carbamylated EPO Fc fusion protein in a Parkinson’s disease model." (PMID 24287913, 2013).
renal cell carcinoma (23 papers, 2006 to 2025). "Moreover VHL-associated tumors such as renal cell carcinomas were described to be causative for elevated Hb or EPO levels." (PMID 30214643, 2018). "Though previously reported, the concomitant finding of an AAA with renal cell carcinoma with a normal erythropoietin levels is surprising." (PMID 31934488, 2019). "The simultaneous presence of angiomyolipoma and renal cell carcinoma has been reported and in that case it was a source of exogenous EPO secretion which was able to be corrected." (PMID 19946506, 2009). "Erythropoietin has been immunolocalized to the cytoplasm of renal cell carcinoma cells in the majority of cases with clinical erythrocytosis." (PMID 16995951, 2006). "EPO is required for erythropoiesis, but can also stimulate angiogenesis, tumor cell proliferation and survival in human renal cell carcinoma (RCC)." (PMID 40332447, 2025). "Two patients with renal cell carcinoma and erythrocytosis had normal EPO levels, a surprising but not an isolated finding." (PMID 34013406, 2021).